TTK (TTK protein kinase)
Diseases named in the same sentence as TTK in open-access papers (continued):
Sharing a sentence is not in itself a finding about the gene and the disease.
glioblastoma (17 papers, 2012 to 2023). The most malignant astrocytic tumor (WHO grade IV). "TTK knockdown in glioblastoma and colorectal cancer cell lines reduced cell viability, led to abnormal cell progression and increased apoptosis." (PMID 37815894, 2023). "TTK is overexpressed in various cancers and serves as a target for the cancer treatment of colon, ovarian, breast, and glioblastoma." (PMID 37815894, 2023). "BAY-1217389 and CFI-402257, two selective TTK inhibitors, greatly decreased glioblastoma multiforme cell proliferation and enhanced the growth-suppressive efficacy of temozolomide." (PMID 36829176, 2023). "Inhibition of TTK enhances the efficacy of docetaxel in a murine triple-negative breast cancer model and promotes the radiosensitivity of glioblastoma." (PMID 34876569, 2021). "Micro-RNAs are important mediators of EMT, and micro-RNA 21 (miR-21), a downstream target of TGF-β involved in EMT, is regulated by TTK in glioblastoma cells." (PMID 30206215, 2018). "TTK inhibition has previously been shown to enhance the radiosensitivity of human glioblastoma cells as well as enhance chromosomal instability and sensitivity of cancer cell lines when combined with the microtubule targeting drugs vincristine or paclitaxel." (PMID 28380042, 2017). "Thus, TTK promotes cancer cell proliferation and invasion, and its upregulation leads to poor prognosis for various cancers of the breast, colon, and glioblastoma." (PMID 37815894, 2023). "Moreover, Mps1-IN-3, a selective small molecule TTK inhibitor, produced mitotic aberrations in glioblastoma cells, and its combination with vincristine increased cell death." (PMID 36829176, 2023). "With this strategy we were able to show that tTK expressing hAMSCs are very effective vehicles to deliver localized cytotoxic therapy to U87 glioblastomas and that hAMSCs within tumors differentiate to endothelial lineage cells that associate with vascular structures." (PMID 22529983, 2012). "Analysis of essential regulators of the G2/M and spindle assembly checkpoints (PLK1, TTK/MPS1), mitotic spindle dynamics (KIF11) and sister chromatid separation (PTTG1/securin) confirmed their down-regulation in a panel of glioblastoma cell lines." (PMID 33478100, 2021). "It has been found that numerous tumors, such as glioblastoma and gastric adenocarcinoma, harbor expression changes in BUB1, BUB1B, and TTK as well as checkpoint dysfunction." (PMID 32090084, 2020). "In support of this hypothesis, overexpression of TTK has been previously observed in multiple tumor types including PDAC, breast, bladder, esophagus, lung, anaplastic thyroid, and glioblastoma." (PMID 28380042, 2017).
ovarian carcinoma (17 papers, 2021 to 2025). A malignant neoplasm originating from the surface ovarian epithelium. "The findings showed that high expression levels of BUB1B, BUB3, or TTK were associated with better survival rates in ovarian cancer patients treated with paclitaxel compared to patients with low expression levels." (PMID 38410481, 2024). "TTK is highly expressed during mitosis and in many cancers such as breast, lung, hepatocellular, ovarian cancer, and others." (PMID 38658569, 2024). "Reported four genes (BUB1B, BUB1, TTK and CCNB1) that were up-regulated DEGs in ovarian cancer associated with poor prognosis using integrated bioinformatical methods." (PMID 39048649, 2024). "In ovarian cancer tissues and cells, TTK expression was upregulated, and its overexpression was discovered to be related to an unfavorable prognosis in ovarian cancer patients." (PMID 36829176, 2023). "In ovarian cancer, knockdown or inhibition of TTK expression was known to drastically restrict cell growth and eliminate cisplatin resistance." (PMID 36829176, 2023). "TTK knockdown increases the sensitivity of cisplatin-resistant ovarian cancer cells to cisplatin via the PI3K/AKT signaling pathway." (PMID 35850753, 2022). "TTK is overexpressed in cisplatin-resistant ovarian cancer cells and ovarian cancer patients with acquired resistance to cisplatin." (PMID 35850753, 2022). "Genetic and pharmacological inhibition of TTK impeded the proliferation of ovarian cancer cells by disturbing cell cycle progression and increasing apoptosis." (PMID 34876569, 2021). "In this study, cisplatin-resistant ovarian cancer cell line A2780 (A2780cis) was established to explore the relationship between TTK expression and cisplatin-resistance." (PMID 34598710, 2021). "In conclusion, inhibition of TTK combined with cisplatin is a potentially effective therapy to overcome the insensitivity or resistance to cisplatin in patients with ovarian cancer." (PMID 34876569, 2021). "TTK was expressed at higher levels in ovarian cancer and other cancers than in the corresponding normal controls in several open access databases." (PMID 34876569, 2021). "The TTK, NEK2, and CDK1 are over-expressed, demonstrating a high frequency of genetic alterations, and are associated with poor prognosis of ovarian cancer cohorts." (PMID 34072728, 2021). "Our study demonstrated that TTK was overexpressed in ovarian cancer, and was further up-regulated in cisplatin-resistant cells." (PMID 34598710, 2021). "In this study, we investigated the roles of TTK in the progression and cisplatin resistance of ovarian cancer." (PMID 34876569, 2021). "The autophagy pathway, one of the top five pathways affected by TTK depletion, has been shown to be involved in cisplatin resistance in ovarian cancer." (PMID 34876569, 2021). "Similar to previous studies, our results identified TTK as an oncogene in ovarian cancer, and inhibition of TTK suppressed the proliferation of ovarian cancer in vitro and in vivo." (PMID 34876569, 2021). "The downregulation of TTK increased the sensitivity of ovarian cancer cells to CDDP, and this effect was partially reversed by rapamycin." (PMID 34876569, 2021). "Next-generation sequencing (NGS) was carried out in A2780 cells transfected with siTTK2 or NC (n = 3) to clarify the potential mechanism by which TTK depletion suppressed the proliferation and increased the sensitivity of ovarian cancer cells to cisplatin." (PMID 34876569, 2021). "MTT assays revealed that TTK silencing significantly enhanced the sensitivity of ovarian cancer cells to CDDP at 24 and 48 h." (PMID 34876569, 2021). "In cisplatin-resistant ovarian cancer cells, TTK was up-regulated compared with the parent tumor cells." (PMID 34598710, 2021).
ovarian carcinoma (continued). "We have earlier reported NSC777201 for some biological activities, herein, we used a molecular docking approach and an NCI’s ovarian cancer cell lines to evaluate its anti-cancer activity and explore its possibility for targeting TTK, NEK2, and CDK1." (PMID 34072728, 2021). "Genetic (shRNA and siRNA) and pharmacological (BAY1217389 and CFI-402257) inhibition of TTK suppressed proliferation and enhanced chemosensitization in ovarian cancer cells." (PMID 34876569, 2021). "In this study, we explored the possibility of sensitivity-reacquisition to cisplatin in ovarian cancer cells through targeting for TTK." (PMID 34598710, 2021). "The level of LC3-II was increased to a greater extent following chloroquine (CQ) treatment, suggesting that TTK induced autophagy in ovarian cancer cells." (PMID 34876569, 2021). "We performed an NGS analysis to determine the underlying mechanism by which TTK inhibition suppressed the growth of ovarian cancer and found that the expression of genes involved in the autophagy pathway was decreased after TTK knockdown." (PMID 34876569, 2021). "Then, we searched two independent cisplatin resistance datasets and found that TTK expression was increased in cisplatin-resistant ovarian cancer cells." (PMID 34876569, 2021). "High TTK expression means poor outcomes for ovarian cancer patients." (PMID 36849137, 2023). "Furthermore, the TTK was not only the hub biomarker of ovarian cancer, but also one significant hub gene of renal cancer, and its expression was up-regulated in the renal cancer." (PMID 36849137, 2023). "TTK depletion inhibited ovarian cancer cell proliferation by disturbing cell cycle progression." (PMID 37815894, 2023). "Patients with high expression of TTK in ovarian cancer have unsatisfactory results." (PMID 36849137, 2023). "However, the function of TTK in ovarian cancer progression and the role of TTK inhibitors in ovarian cancer therapy have not been determined." (PMID 34876569, 2021). "Thus, TTK depletion suppresses autophagy in ovarian cancer cells by activating the mTOR signaling pathway." (PMID 34876569, 2021). "Furthermore, TTK was highly expressed in the tissues of ovarian cancer patients, especially those acquired resistance to cisplatin." (PMID 34598710, 2021). "Our results revealed that TTK inhibition decreased autophagy in ovarian cancer cells." (PMID 34876569, 2021). "Furthermore, we indicated that TTK inhibition is an effective strategy to increase cisplatin sensitivity in ovarian cancer." (PMID 34876569, 2021). "We further investigated whether a TTK inhibitor also increased the sensitivity of ovarian cancer to cisplatin." (PMID 34876569, 2021). "Our study revealed that TTK may be a promising therapeutic target for cisplatin-resistant ovarian cancer." (PMID 34598710, 2021). "TTK was up-regulated in the cisplatin-resistant ovarian cancer cell line." (PMID 34598710, 2021). "Thus, TTK inhibition suppressed the progression of ovarian cancer by activating mTOR and further decreasing autophagy." (PMID 34876569, 2021). "We further explored the expression of TTK in cisplatin-resistant ovarian cancer patients." (PMID 34598710, 2021). "Therefore, the role of TTK in the development of ovarian cancer was further investigated in our study." (PMID 34876569, 2021). "TTK inhibition by CFI also resulted in slower growth of ovarian cancer cells." (PMID 34876569, 2021). "Down-regulation of TTK could recover the sensitivity of cisplatin-resistant ovarian cancer cells to cisplatin treatment." (PMID 34598710, 2021).
ovarian carcinoma (continued). "NSC777201 demonstrated antiproliferative and dose-dependent anticancer activity against the NCI’s ovarian cancer cell lines, and its further evaluation towards TTK, NEK2, and CDK1 inhibition was carried out with in silico docking in a receptor-ligand interaction study." (PMID 34072728, 2021). "Actually, TTK expression was reduced when ovarian cancer cells were treated with cisplatin, indicating that TTK may serve as a chemo-therapeutic target." (PMID 34598710, 2021). "The proliferation of ovarian cancer cells with TTK knockdown was significantly decreased." (PMID 34876569, 2021). "TTK was also upregulated in cisplatin-resistant ovarian cancer cells from two other datasets." (PMID 34876569, 2021). "Furthermore, we used the GEPIA web-based tool to investigate the roles of these genes in ovarian cancer; interestingly, we found that expressions of TTK, NEK2, and CDK1 were correlated with tumor stages." (PMID 34072728, 2021). "Therefore, the cisplatin-triggered upregulation of TTK decreased the cisplatin sensitivity of ovarian cancer through the mTOR/autophagy pathway." (PMID 34876569, 2021). "We speculated that TTK inhibition decreases autophagy through the mTOR pathway in ovarian cancer." (PMID 34876569, 2021). "Nonetheless, the role of TTK in ovarian cancer (OC) remains unclear." (PMID 34516342, 2021). "In conclusion, TTK, NEK2, and CDK1 are strongly associated with tumorigenesis, therapeutic resistance, and poor prognosis of ovarian carcinoma and thus serve as a novel biomarker for diagnosis as well as attractive therapeutic targets for the treatment of ovarian carcinoma." (PMID 34072728, 2021). "Consequently, we speculated that TTK inhibition suppresses ovarian cancer cell proliferation and increases the sensitivity of ovarian cancer cells to cisplatin by inhibiting the autophagy pathway." (PMID 34876569, 2021). "A Kaplan-Meier survival analysis was carried out to determine the relationship between the expression of BUB1B, TTK, and BUB3 and the overall survival and recurrence-free survival of ovarian cancer patients treated with paclitaxel." (PMID 38410481, 2024). "TTK, mTOR, p-mTOR, AKT, p-AKT, 4EBP1, p-4EBP1, Bcl-2 are highly expressed in ovarian cancer, Bax, Caspase3 are lowly expressed in ovarian cancer, and cell apoptosis is inhibited, leading to the deterioration of ovarian cancer." (PMID 36849137, 2023). "Western blotting analysis showed that TTK, mTOR, AKT were highly expressed in ovarian cancer (P < 0.05)." (PMID 36849137, 2023). "The pharmacological and genetic inhibition of TTK, which is involved in the PI3K-AKT pathway, decreases the proliferation of ovarian cancer cells and increases their sensitivity to cisplatin by suppressing autophagy." (PMID 36352420, 2022). "To investigate the roles of TTK, NEK2, and CDK1 overexpression, we mined the TCGA’s ovarian cancer genomics data via the cBioportal website." (PMID 34072728, 2021). "We depleted the expression of TTK in CAOV3 and OV90 cells to investigate the potential function of TTK in ovarian cancer." (PMID 34876569, 2021). "Thus, TTK may be a potential therapeutic target in patients with platinum-resistant ovarian cancer." (PMID 34598710, 2021). "Taken together, TTK silencing enhances CDDP-induced apoptosis and increases the sensitivity of ovarian cancer cells to CDDP." (PMID 34876569, 2021). "The Oncomine database was used for the expression analysis of TTK, NEK2, and CDK1 in ovarian cancer and normal samples." (PMID 34072728, 2021). "Collectively, our study suggested that TTK, NEK2, and CDK1 are novel biomarker signatures of ovarian carcinoma and an attractive target for NSC777201 with consequent anticancer implications." (PMID 34072728, 2021). "The HPA database was used to verify histological levels of TTK, NEK2, and CDK1, and results suggested that TTK, NEK2, and CDK1 were upregulated in ovarian cancer tissue compared to the normal tissue." (PMID 34072728, 2021).
ovarian carcinoma (continued). "This research with aid of bioinformatics, digging at core genes of ovarian cancer and renal cancer, through some experiments to determine whether TTK and AKT-mTOR pathway can affect ovarian cancer and renal cancer." (PMID 36849137, 2023). "But, how TTK and AKT-mTOR pathways affect ovarian cancer and renal cancer is uncertain." (PMID 36849137, 2023). "China recently did a lot of work in the discovery of multiple drug resistance mechanisms, including overexpression of the USP11-BIP axis leading to drug resistance, significantly upregulated TTK expression in high-grade serous ovarian carcinoma (HGSOC), and cisplatin-resistant ovarian cancer cells." (PMID 37324006, 2023). "In summary, TTK and AKT-mTOR pathways affect ovarian cancer." (PMID 36849137, 2023). "In addition to the PPI network, ingenuity pathway analysis also implicate TTK, NEK2, and CDK1 in the elevated salvage pyrimidine and pyridoxal pathways in ovarian cancer." (PMID 34072728, 2021). "TTK was the only gene in the cell cycle pathway with clinical-grade inhibitors that has not been investigated in ovarian cancer." (PMID 34876569, 2021). "TTK expression was obviously upregulated in HGSOC and cisplatin-resistant ovarian cancer cells." (PMID 34876569, 2021). "For instance, four genes (BUB1B, BUB1, TTK, and CCNB1) that are pronouncedly upregulated in ovarian cancer and indicate dismal prognosis were disclosed through bioinformatic methods, and they can be used as potential therapeutic targets for patients with ovarian cancer." (PMID 34434217, 2021).
pancreatic ductal adenocarcinoma (15 papers, 2017 to 2025). An infiltrating adenocarcinoma that arises from the epithelial cells of the pancreas. "Suppression of TTK in pancreatic ductal adenocarcinoma cell lines significantly reduces cell migration and increases cell death by inducing apoptosis, indicating its significant role in pancreatic carcinogenesis." (PMID 40723362, 2025). "We found overexpression of TTK protein in a subset of pancreatic ductal adenocarcinoma primary tumors and cell lines." (PMID 28380042, 2017). "Similarly, in pancreatic ductal adenocarcinoma, H3K18la enrichment regulates mitotic checkpoint regulators TTK and BUB1B transcription to tumorigenesis." (PMID 41310104, 2025). "Similarly, the depletion of TTK decreased colonic survival and increased apoptosis in the pancreatic ductal adenocarcinoma cell line." (PMID 37815894, 2023). "Furthermore, it was found strongly overexpressed in human pancreatic ductal adenocarcinoma, which is consistent with the results obtained in this study, where we found TTK gene upregulated in the tumor tissue of ccRCC patients." (PMID 35954157, 2022). "Tyrosine threonine kinase (TTK) has been shown to be up-regulated in several cancers including lung cancer, gastric cancer, and pancreatic ductal adenocarcinoma, strongly suggesting it may be critical in cell proliferation in tumours." (PMID 36232772, 2022). "siRNAs and shRNAs have also been used to inhibit TTK in pancreatic ductal adenocarcinoma." (PMID 29149186, 2017).
colorectal cancer (14 papers, 2011 to 2025). A primary or metastatic malignant neoplasm that affects the colon or rectum. "Ultimately, experimental validation through quantitative PCR in gastric and colorectal cancer tissue specimens confirmed that the transcript levels of AURKA, CEP55, DTL, and TTK are markedly elevated in tumor tissues compared to normal tissues." (PMID 40723362, 2025). "Besides leukemia, miR-582 has been shown to inhibit the development of solid tumors, including non-small cell lung cancer, bladder cancer, and human colorectal carcinoma, by targeting different gene, such as Hippo-YAP, TTK, and Rab27a." (PMID 35115499, 2022). "Finally, we confirm that the reference compound reversine is a TTK inhibitor and like NTRC 0066-0, inhibits the proliferation of patient-derived colorectal cancer organoids." (PMID 28415765, 2017).